STAT1 (signal transducer and activator of transcription 1)
Diseases named in the same sentence as STAT1 in open-access papers (continued):
Sharing a sentence is not in itself a finding about the gene and the disease.
tumor (continued). "We show that tyrosine kinases engage pY239/240-ShcA to sustain STAT3 immunosuppressive signals and simultaneously employ pY313ShcA to restrain activation of STAT1-driven anti-tumour immunity." (PMID 28276425, 2017). "In the same study, we found that patients with STAT1 low tumors had a significantly worse clinical outcome; gene transfection of STAT1 into ESCC cells was found to effectively induce apoptosis, highlighting the biological importance of STAT1 in this tumor." (PMID 28431406, 2017). "Taken together, these data suggest that tyrosine kinases engage the Y239/240-ShcA phosphorylation sites primarily to potentiate STAT3 immunosuppressive signals and use the Y313-ShcA phosphorylation sites to attenuate STAT1-dependent anti-tumour immunity." (PMID 28276425, 2017). "Our data suggests that elevated STAT3 immunosuppressive signals enable persistent STAT1 activation by limiting its anti-tumour responses and thereby potentiating STAT1-driven, PD-L1-dependent induction of T-cell tolerance." (PMID 28276425, 2017). "In ESCC cells, STAT1β enhances the tumor suppressor function of STAT1 by increasing the expression and activation of STAT1α." (PMID 28981100, 2017). "We now show that the ShcA phosphotyrosine motifs potentiate immune suppression by limiting signal transducer and activator of transcription (STAT)-1-driven anti-tumour immunity, while simultaneously increasing STAT3 immunosuppressive signals." (PMID 28276425, 2017). "The ratios of tumor-infiltrated immune cells to total cell count in WT, KO host, and spontaneous Stat1-null tumors were 8%, 4.5%, and 2.2%, respectively, for CD3+ T lymphocytes and 0.77%, 0.24%, and 0.23% for F4/80 macrophages, respectively." (PMID 28865492, 2017). "In fact, it has been demonstrated that neutralizing antibodies against IFN-β inhibited STAT1 phosphorylation induced by TWEAK in WiDr tumor cells." (PMID 28447667, 2017). "Our group also has recently published that STAT1 plays a tumor suppressor role in ESCC, in which we found that 43 of 57 (75.4%) ESCC samples examined showed a down-regulation of STAT1 as compared to the case-matched, benign epithelia adjacent to the tumors." (PMID 28431406, 2017). "STAT1, which carries tumor suppressor functions in several models, consists of two isoforms, namely STAT1α and STAT1β." (PMID 28981100, 2017). "One component of the JAK-STAT-ISRE signalling pathway considered to have tumour suppressor function is STAT1." (PMID 28344639, 2017). "We also examined the importance of STAT1 in tumours that retain high (MT/ShcA+/+; MT/Shc313F/313F) versus low (MT/Shc2F/2F) STAT3 signalling." (PMID 28276425, 2017). "Tumor cells were pretreated with cisplatin for different time periods, washed and subsequently pulsed with cytokines after which STAT1, STAT3 or STAT6 phosphorylation was assessed." (PMID 28903353, 2017). "Studies have shown that MG markedly increased IFN-γ in Sarcoma180 tumor-bearing mice, and STAT1 can be up-regulated by IFN-γ." (PMID 28903386, 2017). "Studies also showed that IFN-γ upregulated PD-L1 expression on tumor cells via STAT1 phosphorylation." (PMID 28881828, 2017). "STAT1 protein levels in tumor tissues were increased to approximately 1.3-fold in mice treated with 30 mg/Kg MG and 1.7-fold in mice treated with 60 mg/Kg MG relative to that in the tumors of the control group." (PMID 28903386, 2017). "Tumor tissue from mice injected with GBM cells with enforced miR203 expression had lower protein levels of miR203 targets (STAT1, PI3KCA and IVNS1ABP), but the levels of STAT3 and actin were unaffected." (PMID 27705947, 2016). "On the other hand, STAT1 is a prominent tumor suppressor in various cancers, but its precise role in CRC context is unclear." (PMID 27191495, 2016). "The data clearly showed that OSM reduced the number of metastatic tumor nodules in lungs, whereas knockdown of STAT1 abrogated the inhibitory effect." (PMID 27486982, 2016).
tumor (continued). "In contrast, we discovered a substantial difference between Stat1−/− and Stat1-Y701F NK cells in their ability to kill tumor target cells." (PMID 27757297, 2016). "According to previous studies, STAT3 has been shown to promote tumor progression, whereas STAT1 tend to suppress it." (PMID 27486982, 2016). "In keratinocytes and MB cells, SOCS1 was found to be a direct target of GLI2, blocking the IFN-γ/STAT1 pathway and inhibiting cell cycle arrest and downregulating anti-tumor immunity." (PMID 26988232, 2016). "In this versatile context, the identification of individual ISGs contributing to tumor cell resistance downstream of the STING/IFN/STAT1 pathway deserved to be investigated further." (PMID 27791205, 2016). "It has been shown that in some tumor cell lines delivery of control plasmid DNA caused significant increase in the expression of following ISGs: IRF7, STAT1, MIG, MICA and ITGAL." (PMID 26839680, 2016). "Due to the strong association observed between both ph-STAT1 and ph-STAT3 and tumour necrosis, the relationship between ph-STAT1 and ph-STAT3 tumour cell expression with CSS in patients with high tumour necrosis was subsequently examined." (PMID 27769057, 2016). "STAT1 negatively regulates angiogenesis, tumorigenicity, and metastasis of tumor cells by inhibiting the expression of bFGF, MMP-2, and MMP-9." (PMID 26928402, 2016). "This led us to conclude that NK cell-mediated cytotoxicity and tumor surveillance is partially rescued in Stat1-Y701F mice." (PMID 27757297, 2016). "In fact, examination of the effects of C188-9 on STAT1 in each of our in vitro assays, as well as in tumor xenografts, demonstrated that C188-9 was as effective at targeting STAT1 as it was in targeting STAT3." (PMID 27027445, 2016). "Compared with the control uninfected chickens, IRF1 and STAT1 levels were decreased in the tumor samples." (PMID 27252695, 2016). "High ph-STAT1 and ph-STAT3 tumour cell expression were associated with increased ER (both P≤0.001) and PR (both P <0.05), reduced tumour grade (P=0.015 and P<0.001 respectively) and necrosis (both P=0.001)." (PMID 27769057, 2016). "Conclusively, our mechanistic investigation of OSM-dependent tumor suppressive effect not only revealed the involvement of STAT1 to suppress SLUG expression and cellular motility but also provided insight how dominancy of STATs is switched." (PMID 27486982, 2016). "Our findings suggested that OSM suppresses SLUG expression and tumor metastasis of LAC through inducing the inhibitory effect of the STAT1-dependent pathway and suppressing the activating effect of STAT3-dependent signaling." (PMID 27486982, 2016). "Our findings demonstrate that miR203 has tumor suppressive activity by silencing pro-tumorigenic STAT1." (PMID 27705947, 2016). "We focused our analysis on STAT1 as a miR203 target gene because the role of STAT1 in IFN signaling, and STAT1 has been reported to have both tumor suppressive, and protumorigenic activity." (PMID 27705947, 2016). "The relationship between total and ph-STAT1 tumour cell expression and CSS using Kaplan-Meier log rank test was examined." (PMID 27769057, 2016). "Our finding that STAT1 is a miR203 target gene is particularly interesting because STAT1 has been reported to have both tumor suppressive, and protumorigenic activity." (PMID 27705947, 2016). "Ex vivo isolated STAT1–Ser727A mutant NK cells had increased lytic potential against a range of tumor cell lines in vitro and secreted increased levels of granzyme B and perforin." (PMID 27148271, 2016). "There are two key STAT subtypes: STAT3, an oncogene which promotes cell survival and proliferation, and STAT1, a tumour suppressor which induces anti-proliferative and pro-apoptotic responses." (PMID 26909593, 2016).
tumor (continued). "STAT1 is described in carcinomas as a tumor suppressor, particularly attributed to its ability to induce apoptosis and cell cycle arrest, leading to growth inhibition." (PMID 27191495, 2016). "This led us to propose a novel function for STAT1 at the immunological synapse in NK cells regulating tumor surveillance and cytotoxicity." (PMID 27757297, 2016). "The aim of the present study was to examine the relationship between tumour cell expression of total and phosphorylated STAT1 (ph-STAT1) and STAT3 (ph-STAT-3), components of tumour microenvironment and survival in patients with invasive ductal breast cancer." (PMID 27769057, 2016). "STAT1 promotes tumor growth by diverse processes that range from suppression of tumor immune surveillance and an increase in invasiveness/metastasis to acquisition of resistance against irradiation and chemotherapy." (PMID 27863408, 2016). "Tumor development was significantly delayed in Stat1-Y701F mice and only at day 19 post injection tumor nodules were clearly visible." (PMID 27757297, 2016). "High ph-STAT1 and ph-STAT3 tumour cell expression were also significantly associated with reduced tumour recurrence (P=0.003 and P=0.001 respectively)." (PMID 27769057, 2016). "In vivo, STAT1–Ser727A mutant mice showed increased anticancer immunosurveillance against the murine tumor lines B16F10, 4T1, and a v-abl transformed leukemic cell line." (PMID 27148271, 2016). "We then investigated both STAT1 (tumour suppressor) and STAT3 (oncoprotein) activity in JAK/STAT pathway after gefitinib monotherapy." (PMID 26909593, 2016). "IFNγ-activated STAT1 signaling induces apoptosis, halts progression through cell cycle and boosts anti-tumor immunity." (PMID 26988232, 2016). "Consistent with its ability to confer NK cytotoxicity STAT1-Y701F partially restored NK cell-mediated tumor surveillance." (PMID 27757297, 2016). "In univariate analysis, both high ph-STAT1 (P=0.002) and ph-STAT3 (P<0.001) tumour cell expression were associated with improved CSS." (PMID 27769057, 2016). "In contrast, STAT1 induces the anti-proliferative and pro-apoptotic responses in tumor cells, enhances inflammation and innate and adaptive immunity." (PMID 27486982, 2016). "Our previous study has indicated that the mRNA and protein expression of STAT1 were significantly downregulated in the HCC tumor tissues compared to the normal tumor-adjacent tissues." (PMID 26617467, 2015). "Although IL-1β has been known to activate NF-κB signaling in MDSCs to affect tumor progression, IL-1β has recently been reported to influence B16 tumor progression via STAT1 signaling." (PMID 25706411, 2015). "Studies of mammary tumorigenesis in female Stat1 knockout (Stat1-null) mice describe a potential tumor suppressor role for STAT1." (PMID 26075897, 2015). "Suppression of STAT1 in vitro was also observed in patient tumor samples, suggesting STAT1 silencing as a global mechanism of MHC II suppression and immunoevasion." (PMID 25690042, 2015). "Although STAT5 responses can also contribute to anti-tumour immunity, the effects of STAT3 and STAT1 on tumour-associated inflammation are believed to be playing a leading role." (PMID 25880691, 2015). "CAFs lose the ability to trigger growth inhibitory STAT1 signaling in cancer cells, favoring tumor progression and suggesting STAT1 as a link between intestinal inflammation and CRC." (PMID 25853091, 2015). "Initially, IFNγ/STAT1 signaling helps protecting the host from tumor formation and development (immune surveillance), but subsequently IFNγ can also promote the tumors to resist attack (immunoediting) and escape by Darwinian evolution." (PMID 26654227, 2015).
tumor (continued). "STAT1 up-regulation was seen in the co-culture experiments, supporting recent research suggesting an oncogenic role of STAT1 in the tumor microenvironment." (PMID 26231887, 2015). "In the past, STAT1 was seen as a tumor suppressor, however, recent research suggests that up-regulation of STAT1 can promote immunosuppression in the tumor microenvironment causing a more favorable environment for tumor growth." (PMID 26231887, 2015). "Our study showed that ARTD9 can inhibit the IFNγ/STAT1-dependent anti-proliferative and pro-apoptotic activities of tumor suppressor IRF1 while simultaneously activating the STAT1/IRF2-mediated anti-apoptotic-pro-survival pathways in HR-subtype DLBCL cells." (PMID 26654227, 2015). "TAMs gather in the tumour microenvironment in response to cytokines such as Csf1, a STAT1 target gene." (PMID 25915429, 2015). "STAT1 also acts as a negative regulator of tumor angiogenesis partially through the induction of CXCL10." (PMID 26351076, 2015). "The role of the STAT1 cascade in tumor is controversial, and despite strong data indicating that STAT1 downregulation was most prominent in the tumor cells themselves when compared with the surrounding stroma and infiltrating lymphocytes." (PMID 26617467, 2015). "Conversely, one of the largest arguments for STAT1 in cancer progression has been the reverse: a pro-apoptotic protein acting as a tumor suppressor." (PMID 26231887, 2015). "Prior studies of mammary tumorigenesis in Stat1-null mice in other mouse strains and using different molecular constructs have induced tumors either by crossing mice with tumor-prone cNeu transgenic mice or by pregnancy." (PMID 26075897, 2015). "They appear to play opposite roles in tumourigenesis: STAT3 is considered an oncogene because it promotes cell survival/proliferation, while STAT1 enhances inflammation and immunity, triggering anti-proliferative and pro-apoptotic responses in tumour cells." (PMID 25705130, 2015). "STAT1 has been initially considered to act exclusively as tumor suppressor and key regulator of the surveillance of developing tumors, primarily by activating growth-inhibitory and pro-apoptotic signaling in tumor cells, mainly mediated by IRF1." (PMID 26654227, 2015). "The synthetic SIFα inhibits tumor cell growth and blocks cells at the S-G2/M phase by activating the STAT1 pathway." (PMID 26584517, 2015). "Consistent with inhibition of STAT1 activation, Ruxolitinib inhibited IFNγ induction of iNOS expression in the tumor cells." (PMID 26497740, 2015). "Of all STATs, STAT1 is traditionally classified as a tumor suppressive protein which is thought to play a key role in immune surveillance of tumors." (PMID 25669971, 2015). "While the individual or combined effects of these factors remains to be resolved, our data supports the role of STAT1 in maintaining a tumor-suppressive MG microenvironment." (PMID 26075897, 2015). "Through our analyses, we predicted an important FBL between STAT1 and miR-155-5p — the most differentially co-expressed regulator pair between normal and tumor samples." (PMID 26156524, 2015). "This SNP is in the intronic region of the STAT1 gene, IFN-γ transcription factor signal transducer and activator of transcription 1, previously implicated as a tumor suppressor." (PMID 26459564, 2015). "The IFN/STAT1 pathway is a typical signaling pathway that mediates crosstalk between tumor cells and components of the host microenvironment." (PMID 26351076, 2015). "Whereas STAT1 is usually considered to be a tumour suppressor, the role of STAT3 is thought to be oncogenic." (PMID 25880691, 2015). "Our overall results support the concept that STAT1 exerts its tumor suppressor effects in ESCC via its modulation of a host of regulators of apoptosis and cell-cycle progression." (PMID 25438156, 2014).
tumor (continued). "To conclude, our findings support the concept that STAT1 exerts its tumor suppressor effects in ESCC via modulating the expression of key regulators of apoptosis and cell-cycle progression." (PMID 25438156, 2014). "We recently found evidence that STAT1 in esophageal squamous carcinoma (ESCC) cells exerts tumor suppressor function, and it regulates five key regulators of apoptosis or cell-cycle progression, including Bcl-2, Bcl-xL, survivin, cyclin D1 and p21." (PMID 25438156, 2014). "The ability of myofibroblasts isolated from UC or CD patients to activate STAT1 signaling in tumor cells was significantly reduced compared to 18Co and HIF ND fibroblasts." (PMID 24818101, 2014). "STAT1 expression inversely correlated with the depth of tumor invasion and tumor size (p=0.047 and p=0.029, respectively, Chi square)." (PMID 25355139, 2014). "This anti-tumor activity of STAT1 appears to be particularly important at the onset of tumor formation and is supposed to lead to the elimination of transformed cells by the innate and adaptive immune system." (PMID 24725474, 2014). "Correlating with this clinical observation, our prior in-vitro studies using two ESCC cell lines have provided evidence that STAT1 carries tumor suppressor functions in ESCC." (PMID 25438156, 2014). "We believe that these findings are linked to the tumor suppressive effects of STAT1C in ESCC, as previous studies have shown that the relative proportions of STAT1 homodimers, STAT3 homodimers and STAT1:STAT3 heterodimers dictate the cell fate." (PMID 25355139, 2014). "The entire coding region of STAT1 cDNA derived from tumor mRNA of seven ER-positive and two ER-negative mammary tumors exhibiting lowered levels of STAT1 protein was sequenced." (PMID 24725474, 2014). "The experiments revealed a stringent association of protein and mRNA expression levels of CXCL10 and STAT1 in the tumor." (PMID 24725474, 2014). "To demonstrate that factors produced by normal fibroblasts regulate the growth of tumor cells through STAT1 activation, we silenced STAT1 in HCT116 cells." (PMID 24818101, 2014). "One possible explanation for this effect is that the STAT1/STAT3 heterodimers have a distinct role in tumor angiogenesis independent from the role of STAT1 or STAT3 homodimers, but further work is necessary to elucidate this effect." (PMID 24404126, 2014). "Despite the fact that the tumor suppressor function of STAT1 is increasingly recognized, the significance of STAT1 in ESCC has not been clearly defined." (PMID 25355139, 2014). "STAT1, which has been reported to have tumor suppressor functions, is known to regulate cellular differentiation and apoptosis through transcription-dependent as well as transcription-independent mechanisms." (PMID 25438156, 2014). "First, we demonstrated the importance of STAT1 in IFN-γ signaling upstream of IDO expression in tumor cell lines." (PMID 24911872, 2014). "Recently, we studied the biological signficance of STAT1 in ESCC, since STAT1 has been shown to promote apoptosis and carry tumor suppressor functions in different types of cancers." (PMID 25438156, 2014). "Mechanistically, our findings can be potentially attributed to different outcomes of short-term and prolonged STAT1 signaling in the tumor." (PMID 24725474, 2014). "Expression of STAT1 in the tumor epithelium as well as in the stroma cells was shown to contribute to these anti-tumor effects of STAT1." (PMID 24725474, 2014). "At initiation, STAT3 and STAT5 are generally considered to be oncogenic while STAT1 is considered to have a tumor suppressor role." (PMID 24728078, 2014). "STAT1 protein in the stroma correlated with mRNA expression levels only, pointing to a predominant influence of tumor epithelium-expressed STAT1 on the total measured protein levels in extracts of pulverized tissue." (PMID 24725474, 2014). "Balanced STAT1 activity is thus indispensable for functional immunity and prevention of tumor development in mice and men." (PMID 24489749, 2014).